FGF2 (fibroblast growth factor 2)
Diseases named in the same sentence as FGF2 in open-access papers (continued):
Sharing a sentence is not in itself a finding about the gene and the disease.
colorectal cancer (36 papers, 1998 to 2024). A primary or metastatic malignant neoplasm that affects the colon or rectum. "In addition, high levels of FGF-2 in plasma were associated with large tumor size in head and neck cancers and with tumor growth kinetics in advanced colorectal cancer." (PMID 32599808, 2020). "On the other hand, CARMN directly interacted with miR‐5683 and they had a synergistic effect on colorectal cancer growth suppression, through degrading FGF2 mRNA to inhibit Akt/mTOR pathway and induce apoptosis/autophagy." (PMID 39039912, 2024). "Next, the colony formation assay, transwell assay and CCK‐8 experiments indicated that FGF2 promoted colorectal cancer cell proliferation." (PMID 39039912, 2024). "Neutrophils promote the growth of liver metastases from colorectal cancer in mice through fibroblast growth factor 2 (FGF2)-dependent angiogenesis." (PMID 39100676, 2024). "FGF-2 increases in groups with colorectal cancer and reaches significance in the group with moderately differentiated adenocarcinoma (G1 versus control p = 0.9; G2 versus control p = 0.014; G3 versus control p = 0.20)." (PMID 32963755, 2020). "According to the prediction of the top 10 network pharmacology molecular target of WCAF for regulating the immunity of colorectal cancer, we chose FGF-2 for verification." (PMID 33746736, 2020). "This study demonstrated that FGF2 was a target gene of miR-16, and agreed with findings in colorectal carcinoma." (PMID 31262262, 2019). "FGF2 gene expression is correlated with several cancer types, including colorectal cancer." (PMID 37671046, 2023). "The FGF-2-FGFRs-SRC-αvβ5 integrin loop might be explored as candidate therapeutic target to block colorectal cancer invasion." (PMID 25973543, 2015). "Inhibition of serine hydrolase monoacylglycerol lipase (MAGL) and transcription factor SATB2 could reduce tumor burden of colorectal cancer and was correlated with the downregulation of fibroblast growth factor-2 (FGF-2) and vascular endothelial growth factor (VEGF)." (PMID 34182543, 2021). "The synthesis and secretion of fibroblast growth factor 2 (FGF2) by neutrophils in the liver microenvironment drives angiogenesis and growth of nascent colorectal cancer-derived hepatic metastases." (PMID 32849639, 2020). "To further check the role of PRKACB, MECOM, PLA2G4C, FGF2 and FGF in colorectal cancer, we further analyzed the genes involved in the MAPK pathway for their association with patient’s survival using the survExpress online tool." (PMID 28749961, 2017). "FGF2, as a member of the FGF family, has also been verified as a target of miR-16 in colorectal carcinoma." (PMID 26655091, 2016). "To assess the clinical relevance of these in vitro observations, we performed preliminary immunohistochemical stainings for FGF-2 and FGFR1 on human colorectal cancer samples." (PMID 25973543, 2015). "Notably, this process significantly surpasses baseline levels for both FGF-2 and PDGF-AA in colorectal cancer patients." (PMID 38067195, 2023). "We recently reported that colorectal cancer TIC spheroids from some patients depended on basic fibroblast growth factor (bFGF; FGF2) for their proliferation in vitro, which led us to hypothesize that FGFR inhibitors might be efficacious for a subset of colorectal cancer patients." (PMID 32708005, 2020).
hepatocellular carcinoma (36 papers, 2012 to 2025). A malignant tumor that arises from hepatocytes. "This was demonstrated using a double-chamber in vitro assay in which FGF-2 secreted by hepatoma cells induced T-cadherin, an adiponectin related to neovascularization, on liver sinusoidal endothelial cells." (PMID 34638361, 2021). "FGF-2 has been shown to be expressed in human tumors since the late 80s and early in vitro work on hepatoma cell lines demonstrated that almost all cells express FGF-2 at the mRNA level." (PMID 34638361, 2021). "In hepatocellular carcinomas, miR-503 inhibited tumor angiogenesis by down-regulation of FGF2 and VEGFA." (PMID 33762949, 2021). "Consistent with this assumption, FGF2 promoted hepatitis C virion production in hepatoma cells and Zika virus infection of human fetal astrocytes." (PMID 32720440, 2020). "FLT1 can bind to VEGFR-A, VEGFR-B and FGF2 and play an important role in promoting endothelial cell proliferation, survival and angiogenesis in Hepatocellular Carcinoma, Non-Small Cell Lung Cancer and Esophageal Cancer 26-29." (PMID 31632486, 2019). "In hepatocellular carcinoma, the proliferation, migration and invasion of cancer cells were inhibited by miR-497-5p; in non-small cell lung cancer, miR-497-5p suppresses the proliferation and invasion of cancer cells by targeting FGF2." (PMID 36103025, 2022). "Additionally, miR-503 also represses hepatocellular carcinoma tumor angiogenesis by targeting the potent angiogenic factors FGF2 and VEGFA." (PMID 25653011, 2015). "FGF2 is also a target of miR-503 in hepatocellular carcinomas." (PMID 26650737, 2015). "However, deficiency of Arid1a in mouse HCC (hepatocellular carcinoma) cells did not alter several of the angiogenesis-related genes, including Vegfa, Fgf2, Egfl7, Sdf1, Hif1a, Hif2a and Ang1." (PMID 38017409, 2023). "Here, we demonstrated that stiffness contributes to mechanosignal transduction in HSCs, which promotes hepatocellular carcinoma (HCC) cells growth and metastasis through secretion of FGF2." (PMID 34873170, 2021). "miR-503 was found underexpressed in hepatocellular carcinoma (HCC) and was shown to inhibit angiogenesis in vitro and in vivo by downregulating expression of both fibroblast growth factor 2 (FGF2) and vascular growth factor A (VEGFA)." (PMID 26834703, 2015). "As previously discussed, an anti-FGF2 diabody could represent a potential therapeutic agent for the inhibition of metastasis formation and immune escape because it was able to inhibit the anti-PD-L1 expression and EMT in hepatoma cells." (PMID 38473265, 2024). "In one study, an autocrine and paracrine mode of action for VASH2 was found to enhance the expression of FGF-2 and VEGF by nuclear factor-κB upregulation in hepatocellular carcinoma (HCC) cells." (PMID 23426782, 2013).
asthma (35 papers, 2005 to 2025). "Additionally, IL-1β, which is involved in the pathogenesis of asthma, can causes FGF-2 release from chondrocytes, which could promote fibroblast proliferation in the perichondrium and contribute to perichondral fibrosis in asthma." (PMID 41283571, 2025). "Considering the possible role of FGF2 in airway epithelial function, which may be entangled with the immune system and cause persistent chronic inflammation, a more clinically relevant disease model is required to investigate the role of FGF2 in asthma." (PMID 35093168, 2022). "In the present study, we similarly found that FGF2 expression was significantly higher in airway tissues of mice with OVA-induced asthma compared with control mice (P = 0.007)." (PMID 40338656, 2025). "In a mouse asthma model, FGF–2 acts as an inflammation amplifier, promoting the infiltration of inflammatory cells in the mouse airways and recruiting subepithelial neutrophils, leading to excessive secretion of inflammatory mediators." (PMID 40005889, 2025). "Multiple studies have reported increased expression of FGF2 in patients with asthma and animal models of asthma." (PMID 40338656, 2025). "FGF2 plays an important role in asthma and COPD, as it is involved not only in the regulation of inflammatory cells but also in mediating interactions between immune cells and airway structural cells." (PMID 41226620, 2025). "Primary outcomes were asthma control test score, fibroblast growth factor 2, and wall area percentage on RB1 bronchus measured by computed tomography." (PMID 38375524, 2023). "This study aimed to evaluate the efficacy of eradication of fungal infection on airway remodeling due to severe persistent asthma, determined by imaging and FGF-2 expression in the sputum, as the best available marker of airway remodeling." (PMID 38375524, 2023). "Nevertheless, FGF-2 has a converse effect on asthma; accordingly, some studies have indicated that FGF-2 promotes airway inflammation through the FGFR/MAPK/NF-κB pathway in the airway epithelial cells." (PMID 38375524, 2023). "Previous studies have confirmed a significant correlation between FGF-2 levels and the severity of asthma." (PMID 38375524, 2023). "Recently, studies have focused on the immunomodulatory function of FGF2 in chronic inflammatory airway diseases including asthma and chronic obstructive pulmonary disease." (PMID 35990834, 2022). "It was reported that FGF2 was overexpressed in asthma and promoted airway inflammation in airway epithelial cells." (PMID 35990834, 2022). "Further, the upregulation of FGF2 induced by allergens and its resistance to steroid treatments might be implied in other conditions such as uncontrolled allergic rhinitis that has been linked to asthma exacerbation, which is worthy of future study in this context." (PMID 35093168, 2022). "It was demonstrated that FGF2 was predominantly expressed within the bronchi and equally prominent in alveolar areas in asthma groups." (PMID 35093168, 2022). "Our findings suggest that FGF2 is a potential inflammatory modulator in asthma, which can be induced by HDM and acts through the FGFR/MAPK/NF-κB pathway in the airway epithelial cells." (PMID 35093168, 2022). "Through the nasal instillation of rm-FGF2 to the HDM-induced chronic mouse asthma model, FGF2 promotes airway inflammatory cell infiltration in asthma patients, which is IgE- and Th2-independent." (PMID 35093168, 2022). "This study revealed that FGF2 is overexpressed in both bronchial and alveolar areas in asthma patients, localised in AECs, subepithelial basement membrane, and inflammatory cell populations." (PMID 35093168, 2022). "This study revealed that FGF2 expression was consistently upregulated in clinical asthma samples and in HDM-induced asthmatic mouse lungs." (PMID 35093168, 2022). "As expected, an upregulation of FGF2 protein abundance (the 22-kD isoform) was consistently observed in this acute asthma model (1.00 ± 0.14 vs. 5.54 ± 0.55, P = 0.0013)." (PMID 35093168, 2022).
asthma (continued). "In our study, HDM stimulation upregulated FGF2 expression levels in both AECs and the asthma mouse model, and FGF2 pre-treatment recruited subepithelial neutrophils in vivo and promoted IL-1β-induced IL-6 and IL-8 secretion in vitro." (PMID 35093168, 2022). "First, FGF2 expression was characterised in clinical asthma samples and the house dust mite (HDM)-induced mouse chronic asthma model." (PMID 35093168, 2022). "Herein, this review provides the current knowledge on the biology of FGF2, its expression pattern in asthma and COPD patients, and its role as an immunomodulatory factor." (PMID 32300593, 2020). "In this review, we provide a comprehensive analysis of FGF2’s function as an immunomodulatory factor in chronic airway diseases, with emphasis on asthma and COPD." (PMID 32300593, 2020). "Targeting FGF2 and their receptors has already been done in the drug development for cancer and other diseases, where they can potentially be applied to asthma and COPD." (PMID 32300593, 2020). "In the following text, we will review FGF2 as an immunomodulatory factor in airway diseases, particularly asthma and COPD, which hopefully will provide new insight into the inflammation processes in these diseases." (PMID 32300593, 2020). "We previously showed that PTX3 inhibits FGF2 induced cell migration, an important factor contributing to increase smooth muscle mass in asthma." (PMID 26644796, 2015). "Taken together, these data demonstrate that PTX3 has the ability to inhibit FGF2-induced migration of HASMC at least in vitro suggesting its role as potential protective mechanism against remodelling observed in asthma." (PMID 22529962, 2012). "Furthermore, previous studies have demonstrated that, aside from its mitogenic effects when administered alone, FGF2 pretreatment enhances the proliferative response of human ASM cells to various asthma mediators." (PMID 40338656, 2025). "The FGF-2 has proved to contribute to smooth muscle hyperplasia; therefore, it is considered a good marker of remodeling due to chronic inflammation following asthma." (PMID 38375524, 2023). "This indicates that additional mechanisms beyond allergic reactions and Th2 immune responses may account for the pro-inflammatory effect of FGF2 in asthma." (PMID 35093168, 2022). "Further investigations of FGF2 in alveolar cells might shed light on the potential role of FGF2 signalling in mediating distal airway pathological changes in asthma." (PMID 35093168, 2022). "This study aimed to investigate the immunomodulatory role of FGF2 in asthma." (PMID 35093168, 2022). "Several human studies revealed that FGF2 blood level is increased in Crohn’s disease and ulcerative colitis patients and that FGF2 could induce the expression of several proinflammatory genes in asthma." (PMID 34136479, 2021). "This suggests to us that FGF2 could be critical in inflammatory processes, and thus might be a key modulator in chronic inflammatory diseases, such as asthma and COPD." (PMID 32300593, 2020). "Likewise, another study suggested that epithelial FGF2 was significantly more abundant in patients with mild asthma than in healthy subjects." (PMID 32300593, 2020). "While the present evidence suggests FGF2 as an immunomodulatory factor in regulating inflammatory cell recruitment, adhesion, and cell function, unfortunately, there is not much evidence documenting the effect of FGF2 on inflammatory cells in asthma and COPD." (PMID 32300593, 2020). "In this review, we will provide an overview of the immunomodulatory function of FGF2, particularly through airway structural cells-driven processes, identifying raising questions, and proposing future research directions for targeting FGF2 in asthma and COPD." (PMID 32300593, 2020). "In another example, FGF2 significantly increases the levels of macrophage colony-stimulating factor (GM-CSF) in ASMCs, which is critical to activate macrophages in asthma and COPD, indicating a role for FGF2 in immune cell activation." (PMID 32300593, 2020).
asthma (continued). "Therefore, in the next section, we will review the immunomodulatory function of FGF2 in both inflammatory cells and airway structural cells, and discuss the possibility of targeting FGF2 so as to inhibit airway chronic inflammation in asthma and COPD." (PMID 32300593, 2020). "With these studies being performed, a better understanding of FGF2 biology and its immunomodulatory role in asthma and COPD could provide potential alternative options for patients that are unresponsive to current anti-inflammatory treatments." (PMID 32300593, 2020). "Altogether, these data suggest that FGF2 expression is elevated in multiple pulmonary cell types in asthma and COPD, and may be involved in the pathogenesis of chronic inflammatory airway diseases." (PMID 32300593, 2020). "In this scenario, we highlighted FGF2 as an important immunomodulatory factor that mediates the interplay between inflammation and airway structural cells and emphasize FGF2 as a potential therapeutic target for asthma and COPD." (PMID 32300593, 2020). "Recently, research interest has been raised in the immunomodulatory function of FGF2 in asthma and COPD, through its involvement in not only the regulation of inflammatory cells but also its participation as a mediator between immune cells and airway structural cells." (PMID 32300593, 2020). "Fibroblast growth factor 2 (FGF2, also known as basic fibroblast growth factor, bFGF), a potent mitogen for fibroblasts, has been reported to be overexpressed in severe asthma and COPD, particularly patients with exacerbated COPD and smokers with chronic bronchitis." (PMID 32300593, 2020). "Therefore, time is needed to determine how we can use the FGF-2 probing treatment for asthma." (PMID 38375524, 2023). "Furthermore, FGF2 levels in sputum corrected by lung function are biomarkers of asthma severity, indicating that FGF2 may be involved in the pathogenesis of asthma." (PMID 35093168, 2022). "Interestingly, our study in the HDM-induced asthma model suggests that FGF2 protein expressed in alveolar areas is mainly extracellular, which might be attributed to different FGF2 isoforms expressed in peri-bronchial and alveolar areas." (PMID 35093168, 2022). "VEGF and basic fibroblast growth factor (FGF-2), strong modulators of angiogenesis, cause the remodulation and inflammation of bronchial cells which causes several lung disorders like chronic obstructive pulmonary disease (COPD), pulmonary hypertension, asthma and IPF." (PMID 33230600, 2021). "However, FGF-2 could also be involved in fibrosis and tissue remodeling in patients with asthma and COPD33." (PMID 30429461, 2018). "(f) Inhibition of LRP1 significantly alleviated peribronchial inflammation, airway hyperreactivity, and ASM proliferation in mice with OVA-induced asthma, as well as suppressed OVA-induced increases in FGF2 and phosphorylated ERK expression." (PMID 40338656, 2025). "The FGF-2 was introduced as a remodeling biomarker of asthma severity,which is inversely correlated with the FEV1/FVC ratio; therefore, it indicates that increasing the amount of FGF-2 accompanies more severe airway obstruction." (PMID 38375524, 2023). "The present study showed that the 32-week administration of 200 mg/day of itraconazole inhibited the gene expression of the FGF-2, increased the percentage of FEV1/FVC, and decreased asthma attacks and wheezing." (PMID 38375524, 2023). "Western blot analysis showed increased levels of PDGF-BB, VEGF, FGF-2, and TGF-β in vehicle-treated asthma lungs, compared to the sham control group." (PMID 36755351, 2023). "The superiority of itraconazole on FGF-2, FEV1/FVC, asthma attacks, and wheezing on chest auscultation during the treatment period compared with prednisolone in patients with severe asthma step 5 demonstrated that itraconazole was better than prednisolone." (PMID 38375524, 2023).